PATL1 (PAT1 homolog 1, processing body mRNA decay factor)
Description:
RNA-binding protein involved in deadenylation-dependent decapping of mRNAs, leading to the degradation of mRNAs. Acts as a scaffold protein that connects deadenylation and decapping machinery. Required for cytoplasmic mRNA processing body (P-body) assembly. (Microbial infection) In case of infection, required for translation and replication of hepatitis C virus (HCV).
Synonyms: Pat1b; hPat1b; FLJ36874
Tractability: PROTAC: ubiquitination databases record sites on it; its protein half-life has been measured.
Gene: Protein-coding gene on chromosome 11 (59,636,716 to 59,669,141, reverse strand). Ensembl gene ENSG00000166889.
Subcellular location: Cytoplasm, P-body; Nucleus; Nucleus, PML body; Nucleus speckle
Subcellular location (Human Protein Atlas): Cytoplasmic bodies
Pathways (Reactome):
Metabolism of RNA: mRNA decay by 5' to 3' exoribonuclease
Gene Ontology:
Molecular function: poly(G) binding; poly(U) RNA binding; protein binding; RNA binding
Biological process: deadenylation-dependent decapping of nuclear-transcribed mRNA; P-body assembly
Cellular component: CCR4-NOT complex; cytoplasmic ribonucleoprotein granule; nuclear speck; nucleus; P-body; cytosol; cytoplasm; PML body
Genetic constraint (gnomAD): Loss-of-function variants: 25 observed, 88.4 expected, observed/expected ratio (o/e) 0.28, 90% interval 0.2 to 0.4. The upper end of that interval is the gene's LOEUF score, 0.4, which puts it in group 1 of 6, group 1 being the genes least tolerant of losing a copy. Missense variants: 712 observed, 909.36 expected, observed/expected ratio (o/e) 0.78, 90% interval 0.74 to 0.83. Synonymous variants: 321 observed, 323.89 expected, observed/expected ratio (o/e) 0.99, 90% interval 0.9 to 1.09.
Homologues: Orthologues: macaque PATL1 (98% identical), dog PATL1 (97% identical), pig PATL1 (97% identical), mouse Patl1 (96% identical), rat Patl1 (96% identical), rabbit PATL1 (93% identical), guinea pig PATL1 (92% identical), chimpanzee PATL1 (90% identical), tropical clawed frog patl1 (53% identical), zebrafish patl1 (48% identical), Drosophila melanogaster Patr-1 (24% identical), Caenorhabditis elegans patr-1 (19% identical). Paralogues in human: PATL2 (24% identical).
Diseases named in the same sentence as PATL1 in open-access papers:
PATL1 is named in the same sentence as 10 diseases in open-access papers, as found by Europe PMC text mining. Sharing a sentence is not in itself a finding about the gene and the disease. The quoted sentences say what the papers report.
breast carcinoma (1 paper, 2024). "Two of them, PATL1 and PRRC2B were discussed earlier; SENP7 is a marker of poor prognosis in colon cancer; SPAG9 is expressed in a variety of malignancies and regulated by QKI in lung cancer; UBR5 promotes postsurgical breast cancer lung metastases, and NSD1 exerts tumor suppressive functions." (PMID 39664813, 2024).
head and neck squamous cell carcinoma (1 paper, 2024). A squamous cell carcinoma that arises from any of the following anatomic sites: lip and oral cavity, nasal cavity, paranasal sinuses, pharynx, larynx, and salivary glands. "The other gene is PATL1 (also known as PAT1b), which has been identified as a prognostic factor for nasal-type natural killer/T-cell lymphoma and head and neck squamous cell carcinoma." (PMID 39664813, 2024). "A similar examination of head and neck squamous cell carcinoma paired samples (n = 43) revealed a significant increase in PATL1 PE skipping (the mean ΔΨ = −0.03, P = 0.02)." (PMID 39664813, 2024).
Stroke (1 paper, 2022). Sudden impairment of blood flow to a part of the brain due to occlusion or rupture of an artery to the brain. "Four of these variants (TPTE rs143510517, MEP1A rs62619974, DDX31 rs142792732, and PATL1 rs79336999) were associated with stroke at p < 1 × 10−10." (PMID 36672803, 2022).
viral infection (1 paper, 2016). "It was observed that a viral infection may disrupt PATL1-localization at P-bodies as the sites of mRNA degradation and sequestrate PATL1 to the vicinity of lipid droplets." (PMID 27034888, 2016).
PATL1 also shares sentences with these, for which no sentence is quoted: tumor (2 papers); adenovirus infection (1); cancer (1); colon cancer (1); infection (1); lung carcinoma (1).